SDS (serine dehydratase)
Description:
Catalyzes the pyridoxal-phosphate-dependent dehydrative deamination of L-threonine and L-serine to ammonia and alpha-ketobutyrate and pyruvate, respectively.
Synonyms: SDH; hSDH
Tractability: Small molecule: it has a high-quality binding pocket. PROTAC: its protein half-life has been measured.
Gene: Protein-coding gene on chromosome 12 (113,392,423 to 113,426,301, reverse strand). Ensembl gene ENSG00000135094.
Subcellular location: Cytoplasm
Subcellular location (Human Protein Atlas): Cytosol; Mitochondria
Pathways (Reactome):
Metabolism: Serine metabolism; Threonine catabolism
Gene Ontology:
Molecular function: L-serine ammonia-lyase activity; protein binding; protein homodimerization activity; pyridoxal phosphate binding; threonine deaminase activity
Biological process: L-serine catabolic process; pyruvate biosynthetic process; L-threonine catabolic process; amino acid metabolic process; gluconeogenesis
Cellular component: cytoplasm; cytosol
Genetic constraint (gnomAD): Loss-of-function variants: 22 observed, 32.27 expected, observed/expected ratio (o/e) 0.68, 90% interval 0.49 to 0.97. The upper end of that interval is the gene's LOEUF score, 0.97, which puts it in group 4 of 6, group 1 being the genes least tolerant of losing a copy. Missense variants: 375 observed, 445.74 expected, observed/expected ratio (o/e) 0.84, 90% interval 0.77 to 0.92. Synonymous variants: 176 observed, 192.57 expected, observed/expected ratio (o/e) 0.91, 90% interval 0.81 to 1.04.
Homologues: Orthologues: chimpanzee SDS (99% identical), macaque SDS (98% identical), dog SDS (91% identical), rabbit SDS (88% identical), rat Sds (84% identical), mouse Sds (84% identical), guinea pig SDS (81% identical), pig SDS (80% identical), tropical clawed frog sds (71% identical), Caenorhabditis elegans cysl-1 (20% identical), Caenorhabditis elegans cysl-2 (20% identical), Caenorhabditis elegans F01D4.8 (19% identical), and 4 more. Paralogues in human: SDSL (60% identical), CBS (23% identical), SRR (20% identical), THNSL1 (18% identical), THNSL2 (17% identical).
Diseases named in the same sentence as SDS in open-access papers:
SDS is named in the same sentence as 15 diseases in open-access papers, as found by Europe PMC text mining. Sharing a sentence is not in itself a finding about the gene and the disease. The quoted sentences say what the papers report.
breast carcinoma (2 papers, 2013 to 2025). "Based on the TCGA-TNBC dataset analysis, four out of the five model genes (SDS, RDH12, IDO1, and GLDC) demonstrated significantly elevated expression levels in breast cancer samples." (PMID 40217479, 2025).
chlamydial infections (1 paper, 2024). "Second, unlike serine dehydratase, datasets in the Human Protein Atlas reveal SRR to be expressed broadly in multiple tissues, including mucosal surfaces associated with chlamydial infections such as the eye and the female reproductive tract." (PMID 38718865, 2024).
Insulin resistance (1 paper, 2022). Increased resistance towards insulin, that is, diminished effectiveness of insulin in reducing blood glucose levels. "The depletion of pyruvate in these pathways can be replenished from glycine by serine dehydratase and serine hydroxymethyl transferase, thereby reducing glycine and serine levels during insulin resistance or obesity." (PMID 35774538, 2022).
pancreatic cancer (1 paper, 2019). "Since serine can be converted to pyruvate via the action of serine dehydratase, we postulated that the serine biosynthesis pathway may be one way to circumvent PKM1/2 knockdown in pancreatic cancer cells." (PMID 31893043, 2019).
cancer (1 paper, 2021). A tumor composed of atypical neoplastic, often pleomorphic cells that invade other tissues. "Of these genes, six lncRNA (AL360091.3, AL360175.1, AC025254.1, AC093801.1, AC092354.1 and AC016722.1); four pseudogenes (RBM22P2, AC073324.1, OR1X1P, RPL7P52 and MTND5P25) and coding SLC36A2 and SDS and have not previously been shown to be transcripts in cancer." (PMID 34026616, 2021).
tumour (1 paper, 1988). "Serine dehydratase and serine aminotransferase activities were absent, whereas 3-phosphoglycerate dehydrogenase and serine hydroxymethyltransferase activities were markedly increased in both tumour types." (PMID 3126791, 1988).
SDS also shares sentences with these, for which no sentence is quoted: sarcoma (2 papers); cognitive decline (1); colon carcinoma (1); COVID-19 (1); Hyperglycemia (1); infection (1); injury (1); Obesity (1); respiratory disease (1).